VDR (vitamin D receptor)
Diseases named in the same sentence as VDR in open-access papers (continued):
Sharing a sentence is not in itself a finding about the gene and the disease.
colorectal cancer (continued). "Additionally, in 2017, we also found that APOM increased the levels of vitamin D receptor (VDR) in colorectal cancer cells, suggesting that APOM may play an antineoplastic role by upregulating the expression of VDR11." (PMID 33173129, 2020). "The expression of the vitamin D receptor (VDR) is closely related to the initiation and development of colorectal carcinoma (CRC), but its regulatory mechanism in CRC stem cells is still unclear." (PMID 32900990, 2020). "Furthermore, because we observed no apparent association between plasma 25(OH)D and colorectal cancer risk in our previous study, we reevaluated this association in consideration of VDR polymorphism." (PMID 27736940, 2016). "Ethnicity-dependent VDR activity, as reflected in CAMP gene expression, may explain differential disease predisposition, as illustrated by the higher prevalence of TB and colorectal cancer in Africans compared to Whites." (PMID 23805323, 2013). "Wang9 found that miR-372 and miR-373 enhance the stemness of colorectal cancer cells by inhibiting the expression of differentiation genes such as NFkB, MAPK/Erk, and vitamin D receptor (VDR)." (PMID 38167930, 2024). "In the early stages of colorectal cancer (CRC), high levels of CYP27B1 and VDR are found in well-differentiated tumors, with levels decreasing in less differentiated tumors." (PMID 39201651, 2024). "The cumulative methylation levels of the VDR and CYP24A1 were significantly lower in colorectal cancer cases than those in controls (P < 0.05)." (PMID 37644572, 2023). "Colorectal cancer (CRC) is a common disease threatening human lives worldwide, and vitamin D receptor (VDR) contributes protective roles in this disease." (PMID 37046222, 2023). "In Model 2, the value of cumulative methylation of VDR and CYP24A1 at significant CpG sites in the diagnosis of colorectal cancer was evaluated." (PMID 37644572, 2023). "For example, miR-372 and miR-373 enhance the stemness of colorectal cancer cells by repressing the expression of differentiation genes, such as NFkB, MAPK (mitogen-activated protein kinase-like protein)/Erk, and VDR (vitamin D receptor)." (PMID 34575133, 2021). "In two colorectal cancer cell lines, HCT116 and SW480 knock down of HDAC3 increased VDR expression and restored sensitivity of these cells to 1,25-D3." (PMID 24808866, 2014). "At present, VDR ChIP-seq data are available from i) GM10855 and GM10861 lymphoblastoid cells, ii) THP-1 monocyte-like cells, iii) LS180 colorectal cancer cells and iv) LX2 hepatic stellate cells reported 1,600-6,200 VDR-specific binding sites." (PMID 24787735, 2014). "The present study describes another mode of crosstalk between the VDR and β-catenin pathways by demonstrating that TCF7L2/TCF-4, itself, is regulated by VDR/1,25(OH)2D3 in human colorectal cancer cell lines and likely in the mammary gland as well." (PMID 19924301, 2009). "The absence of VDR accelerates the progression from chronic colitis to colorectal cancer, highlighting its protective role in this transition." (PMID 40791849, 2025). "Meanwhile, VDR expression in tumor cells and stroma was shown to be independent of patient prognosis in colorectal cancer (CRC)." (PMID 38600588, 2024). "Only one study including 658 patients with colorectal cancer noted that VDR expression did not correlate with patient PFS (HR = 0.94; 95% CI = 0.75–1.43)." (PMID 37561808, 2023). "Chromatin immunoprecipitation sequencing (ChIP-seq) in GM10855 and GM10861 lymphoblastoid cells, undifferentiated and lipopolysaccharide-differentiated THP-1 monocytes, LS180 colorectal cancer cells and LX2 hepatic stellate cells revealed between 1000 and 13,000 VDR-specific genomic binding sites." (PMID 24808867, 2014). "Consequently, to further determine the effects of VDR and its classical ligand on TCF-4 expression, we assayed several colorectal cancer cell lines for changes in TCF-4 expression in response to 1,25(OH)2D3." (PMID 19924301, 2009).
colorectal cancer (continued). "Genome-wide screening using non-prostate cell lines (immune cells and colorectal cancer cells) recently identified over 10,000 new VDR-binding sites, and many cytokines, cytokine receptors, and other immune-related genes were identified as VDR targets." (PMID 26941739, 2016).
prostate carcinoma (106 papers, 2001 to 2026). A carcinoma that arises from epithelial cells of the prostate gland. "In the genotype analysis, men who are homozygote for the rare allele for VDR SNP rs2107301 had a 2.5-fold higher risk of prostate cancer compared with those who are homozygote for the common allele (95% CI: 1.52–4.00; p = 0.002)." (PMID 40630116, 2025). "According to an updated investigation, there is a possibility that the Fok1 VDR polymorphism raises the risk of prostate cancer in Caucasians." (PMID 39335182, 2024). "A high expression of VDR is strongly linked to a lower chance of prostate cancer progression and cancer-related death." (PMID 37242266, 2023). "Prostate cancer is a heritable disease, and an individual's genotype, such as vitamin D receptor polymorphisms, modulates its association with the vitamin D status." (PMID 35229338, 2022). "VDR recruits NCOR1 to negatively regulate vitamin-D3-mediated transcription and physical recruitment of NCOR1 on VDR gene targets was associated with altered repression of chromatin marks in prostate cancer." (PMID 34503224, 2021). "Individuals that carried tumors with the highest VDR expression had significantly reduced risk of developing lethal prostate cancer or prostate cancer." (PMID 34199743, 2021). "Previous studies have shown that VDR genetic variants (such as rs1544410, rs7975232 and rs731236) can participate in the development of various tumors (such as prostate cancer and hepatocellular carcinoma) by affecting the biological effects of vitamin D." (PMID 32000758, 2020). "High VDR expression in prostate cancer clinical samples was associated with a reduced risk of lethal cancer, suggesting an antioncogenic role of the vitamin D pathway in prostate cancer progression." (PMID 31212954, 2019). "Previous prospective epidemiological studies performed in various solid cancers (i.e., pancreatic cancer, melanoma, and prostate cancer) demonstrated a strong association between the minor allele VDR rs7299460-T and longer OS or cancer-specific survival." (PMID 31850208, 2019). "Numerous previous studies reported the association of Vitamin D receptor gene Taq Ipolymorphism with prostate cancer risk, however these results were controversial." (PMID 29467956, 2018). "As compared with the homozygote for the common allele, men who were homozygote for the rare allele for VDR rs2107301 have higher risk of prostate cancer." (PMID 28489590, 2017). "On the other hand, vitamin D receptor (VDR) polymorphisms were associated with the incidence of prostate cancer." (PMID 28423553, 2017). "Seven studies involved 4979 cases and 4380 controls related to VDR Cdx2 polymorphism and prostate cancer risk, and 11 studies involved 2837 cases and 2884 controls related to VDR ApaI polymorphism." (PMID 27553621, 2016). "We excluded 266 studies unrelated to Vitamin D receptor (VDR) gene polymorphism, three studies unrelated to prostate cancer, and three reviews." (PMID 27553621, 2016). "We, therefore, investigated the role of VDR Cdx2 and ApaI polymorphisms in prostate cancer risk by conducting a meta-analysis of all the eligible case-controlled studies." (PMID 27553621, 2016). "The role of VDR Cdx2 and ApaI polymorphisms in prostate cancer was unclear due to ethnic variation in genotypes, controls and subjects, and genotyping techniques." (PMID 27553621, 2016). "VDR variants, Bsm1, Taq1, Apa1, and Fok1, have been examined closely for their effects on prostate cancer risk." (PMID 28036013, 2016). "The relationship between VDR Cdx2 and ApaI polymorphisms, and prostate cancer risk in previous studies is attributed to differences in lifestyle and disease prevalence as well as limited sample size." (PMID 27553621, 2016). "Among the known VDR polymorphisms, the most common SNPs, influencing the VDR expression in prostate cancer include FokI, BsmI, ApaI, Cdx2, and TaqI." (PMID 27553621, 2016).
prostate carcinoma (continued). "As calcium mediates the effects of vitamin D in the body, variants of the VDR transcription factor binding sites have been shown to play an important role in the expression of genes that regulate prostate cancer development." (PMID 28036013, 2016). "Odds ratios (ORs) and 95 % confidence intervals (CIs) were analyzed to determine the association between VDR Cdx2 and ApaI polymorphisms, and prostate cancer risk." (PMID 27553621, 2016). "Environmental interaction with VDR Cdx2 and ApaI polymorphisms and its role in prostate cancer risk needs to be validated." (PMID 27553621, 2016). "Together, this data indicates a need for additional investigations into the association between aggressive prostate cancer and VDR SNPs, such as rs11568820." (PMID 28036013, 2016). "Among men in the lowest tertile of 25(OH)D, there was an association between three VDR SNPs (rs11574143, rs757343, BsmI) and prostate cancer risk (the strongest association was for rs11574143: OR 2.49, 95 % CI 1.51, 4.11)." (PMID 25488826, 2015). "Regarding VDR polymorphisms, stronger associations of advanced prostate cancer have been shown with VDR genotypes ff and AA of the polymorphisms FokI and CDX-2 respectively, in the presence of adequate levels of ultraviolet radiation." (PMID 26346690, 2015). "A recent meta-analysis, including thirty-four studies for a total of 10,267 cases and 11,489 controls, focused on the association between vitamin D receptor (VDR) polymorphisms, which mediate the cellular effects of vitamin D and risk of prostate cancer." (PMID 24976856, 2014). "It has been reported that there is an association between the most commonly recognized polymorphisms in the VDR variants such as Cdx2, Fokl, Bsml, Apal, Taql, and the poly-A microsatellite and prostate cancer." (PMID 24282788, 2013). "Deregulation of VDR-associated co-activators and repressors has been associated with impaired sensitivity to 1,25D in a variety of breast and prostate cancer cell lines." (PMID 23341935, 2013). "Odds ratios and 95% confidence intervals of PAWR and VDR SNPs significantly associated with prostate cancer." (PMID 21358824, 2011). "Accordingly, a number of studies have demonstrated links between VDR polymorphisms and risk of a variety of cancers including skin, breast, colorectal and prostate cancer." (PMID 22136443, 2011). "Similar to our results, an association between UV exposure and VDR haplotypes comprised of the rs2254210 SNP was reported in a recent British prostate cancer case-control study." (PMID 20049159, 2010). "A two-fold increase in prostate cancer risk was observed for two VDR loci (rs2107301 and rs2238135), which were located within introns 2 and 4, respectively." (PMID 19753122, 2009). "Associations between the VDR gene polymorphism and prostate cancer risk were calculated in an unconditional logistic regression model." (PMID 19961572, 2009). "Since there is a series of VDR gene polymorphisms that are in strong linkage disequilibrium with one another, some VDR haplotypes have also been reported to be linked with prostate cancer." (PMID 19961572, 2009). "Molecular epidemiological studies have shown that gene polymorphisms of vitamin D receptor (VDR) are associated with prostate cancer risks." (PMID 19961572, 2009). "In prostate cancer patients, the Fok1 ff VDR polymorphism when associated with low plasma vitamin D levels conferred the highest risk of prostate cancer in the USA as well as giving rise to more aggressive tumours." (PMID 19649299, 2009). "Polymorphic variants of the VDR gene have been suggested to be associated with prostate cancer risk and/or a more aggressive phenotype." (PMID 19961572, 2009). "The Cdx2 polymorphism has been associated with risk for bone fracture and with risk for prostate cancer in 25(OH)D deficient men; the VDR-5132 polymorphism has been related to risk for prostate cancer." (PMID 18419802, 2008).
prostate carcinoma (continued). "The relations between VDR polymorphism and prostate cancer remained the same, and the inverse associations of plasma vitamin D levels with risk of prostate cancer were attenuated but remained significant, when the men of non-European descent were excluded." (PMID 17388667, 2007). "The only study on the joint associations of circulating vitamin D levels and the VDR BsmI polymorphism with prostate cancer came from our group, showing that the BsmI BB genotype was associated with lower risk among men with low 25(OH)D status." (PMID 17388667, 2007). "In a study of prostate cancer, Ma and coworkers reported that vitamin D intake modified the risk for prostate cancer that was associated with VDR polymorphism (BsmI)." (PMID 18067661, 2007). "In this study, the researchers have investigated how levels of 25(OH)D and 1,25(OH)2D in combination with different VDR FokI alleles are influencing prostate cancer risk." (PMID 17388667, 2007). "Despite intriguing results from laboratory studies, previous epidemiological studies showed inconsistent associations of circulating levels of 25(OH)D, 1,25(OH)2D, and several VDR polymorphisms with prostate cancer risk." (PMID 17388667, 2007). "In addition, specific polymorphisms in VDR gene have been associated with prostate cancer risk in studies of prostate cancer." (PMID 40630116, 2025). "Furthermore, men who are homozygote for the rare allele for the VDR SNP rs2238135 have a 2-fold higher risk of prostate cancer compared with those who are homozygote for the common allele (95% CI: 1.17–3.26; p = 0.007." (PMID 40630116, 2025). "Another study suggested that the Fok1 VDR polymorphism might be a viable target to predict the risk of prostate cancer." (PMID 39335182, 2024). "VDR gene polymorphisms are associated with colon, breast, kidney, and prostate cancers." (PMID 33226370, 2020). "In addition, genetic polymorphisms in VDR were associated with prostate cancer susceptibility and prostate cancer progression." (PMID 31212954, 2019). "VDR has been extensively investigated in association with prostate cancer pathogenesis." (PMID 31212954, 2019). "Some research suggests that the vitamin D receptor (VDR) gene is important in the onset and progression of prostate cancer and VDR gene polymorphisms might be associated with prostate cancer risk." (PMID 31194807, 2019). "Given that the patient data demonstrate heterogeneity of ERG expression in TMPRSS2:ERG positive prostate cancer, we cannot completely exclude the possibility that VDR-mediated induction of ERG will cause an increase in ERG activity in cells with low basal levels of TMPRSS2:ERG expression." (PMID 28591703, 2017). "These novel functions contrast with the known anti-proliferative nuclear actions of the liganded VDR and may represent targets for new diagnostic and therapeutic approaches in breast and prostate cancer." (PMID 28944088, 2017). "Polymorphisms or miRNA regulation associated with the VDR could affect prostate cancer risk or PSA levels." (PMID 28417914, 2017). "Targeting the unliganded VDR may open up new avenues for the development of novel diagnostic and therapeutic approaches in breast and prostate cancer." (PMID 28944088, 2017). "Finally, most studies investigating the VDR Cdx2 polymorphism in prostate cancer risk involved Caucasian population." (PMID 27553621, 2016). "Vitamin D receptor (VDR) gene polymorphisms affect the risk of prostate cancer." (PMID 27553621, 2016). "However, studies investigating the relationship between VDR gene polymorphisms (Cdx2 and ApaI) and prostate cancer risk are equivocal." (PMID 27553621, 2016). "Notably, gene polymorphisms of VDR and its metabolites are associated with several forms of cancer (including lung, breast, colorectal, and prostate cancer), multiple sclerosis, chronic obstructive pulmonary disease, and type I diabetes." (PMID 26924988, 2016).